BCR (BCR activator of RhoGEF and GTPase)
Diseases named in the same sentence as BCR in open-access papers (continued):
Sharing a sentence is not in itself a finding about the gene and the disease.
hydrops fetalis (1 paper, 2025). Hydrops fetalis is a severe and challenging fetal condition usually defined as the excessive accumulation of fetal fluid within the fetal extravascular compartments and body cavities that manifests as edema, pleural and pericardial effusion and ascites. "Within the whole cohort, 5 reports included a mention of hydrops fetalis and BCR::ABL1 TKI exposure: one was associated with imatinib, three with dasatinib, and one with nilotinib." (PMID 40442861, 2025). "The findings of our disproportionality analysis study present substantial evidence that BCR::ABL1 TKI exposure is associated with the occurrence of pregnancy complications such as hydrops fetalis, polyhydramnios among fetuses or newborns, which were more specific to dasatinib." (PMID 40442861, 2025).
Insulin resistance (1 paper, 2025). Increased resistance towards insulin, that is, diminished effectiveness of insulin in reducing blood glucose levels. "Additionally, BCR is linked to a heightened risk of insulin resistance." (PMID 40110543, 2025).
kidney injury (1 paper, 2022). Trauma to the kidney. "Thus, DDR1 contributes to acute and chronic kidney injury by regulating BCR and STAT3 phosphorylation and in turn the production of MCP-1 and TGF-β." (PMID 34941574, 2022). "Overall, we identified BCR and STAT3 as key players in DDR1-mediated proinflammatory and profibrotic effects after kidney injury." (PMID 34941574, 2022).
lactic acidosis (1 paper, 2021). Metabolic acidosis characterized by the accumulation of lactate in the body. "In these zones, lactate and glutamine may ensure an energetic level sufficient for the maintenance of the BCR/Abl-independent cell subset, while lactic acidosis may eventually inhibit HIF and induce an “oxidative” metabolic profile, as demonstrated in solid tumors." (PMID 34503182, 2021).
latent infection (1 paper, 2025). "The EBV membrane protein LMP2A mimics BCR signals, thereby sustaining EBV's latent infection within B cells." (PMID 39866943, 2025).
liver cirrhosis (1 paper, 2025). "This study assesses the link between BCR and overall mortality in critically ill liver cirrhosis patients using data from the Medical Information Mart for Intensive Care (MIMIC) database data, exploring BCR’s potential as a prognostic biomarker." (PMID 40110543, 2025). "We propose that a high BCR correlates with negative inpatient clinical outcomes in critically ill liver cirrhosis patients." (PMID 40110543, 2025).
lung fibrosis (1 paper, 2022). "Loss of inhibitory molecules, either CD22 or CD72, decreased skin and lung fibrosis revealing a role for both negative co-receptors of BCR signaling in disease pathogenesis." (PMID 35860745, 2022).
Lyme disease (1 paper, 2024). Lyme disease (named after the towns in the USA where the disease was first identified) is a bacterial infection caused by Borrelia burgdorferi. "Moreover, the availability of bulk plasmablast BCR sequences, as well as single-cell paired BCR sequences from patients with Lyme disease opens the door to detailed antibody reactivity profiles and links to disease manifestations." (PMID 40017585, 2024).
meningitis (1 paper, 2025). A disorder characterized by acute inflammation of the meninges of the brain and/or spinal cord. "It is noteworthy that meningitis-related parameters exert minimal influence on model outcomes (with BCR fluctuations not exceeding 0.002)." (PMID 40733740, 2025).
multiple sclerosis (1 paper, 2021). A progressive autoimmune disorder affecting the central nervous system resulting in demyelination. "Another neighboring gene, CLEC16A, is a C-type lectin that has been implicated in BCR-dependent HLA-II pathway, and within the susceptibility locus for multiple sclerosis (MS)." (PMID 34352044, 2021).
myositis (1 paper, 2023). "Additionally, whether tissue-restricted or overlapping BcR clones are disease-associated and whether they produce myositis-related antibodies warrants further investigation." (PMID 36321862, 2023). "To the best of our knowledge, we report for the first time the presence of B cells carrying the same BcR signatures in muscle tissue and peripheral blood of treatable myositis patients." (PMID 36321862, 2023). "Future work tailored towards a better understanding of the pre-treatment BcR repertoire in myositis patients might result in the identification of biomarkers that could predict eventual response to IVIG treatment." (PMID 36321862, 2023). "Because the pathogenesis of myositis is different for each antibody, we investigated whether different myositis subtypes would show different BcR clonality patterns or repertoire features." (PMID 36321862, 2023). "We next investigated whether the different myositis subtypes showed different BcR clonal repertoires (the number and impact of dominant BcR clones) as well as other BcR repertoire features such as CDR3 length, CDR3 charge and VJ gene usage." (PMID 36321862, 2023). "To fill this gap we used RNA-based next generation sequencing to study the B-cell receptor (BcR) repertoire in baseline muscle tissue and in peripheral blood before and 9 weeks after IVIG treatment in treatment-naive myositis patients." (PMID 36321862, 2023).
neuroblastoma (1 paper, 2020). Neuroblastoma (NB) is the most common solid, extracranial childhood tumor. "However, PON does not affect neuroblastoma cells through the chimeric protein BCR-ABL, since it is not found in this pediatric malignancy, but rather through other TKs, such as FGFR1 or EGFR." (PMID 32962733, 2020).
non-Hodgkin lymphoma (1 paper, 2019). Distinct from Hodgkin lymphoma both morphologically and biologically, non-Hodgkin lymphoma (NHL) is characterized by the absence of Reed-Sternberg cells, can occur at any age, and usually presents as a localized or generalized lymphadenopathy associated with fever and weight loss. "SYK inhibition has been shown to reduce the viability of Non-Hodgkin lymphoma cells by disruption of BCR signaling." (PMID 31645904, 2019).
pancreatitis (1 paper, 2017). Inflammation of the pancreas. "Ponatinib, a pan-BCR-ABL tyrosine kinase inhibitor for the treatment of chronic myeloid leukemia (CML), causes severe side effects including vascular occlusions, pancreatitis, and liver toxicity, although the underlying mechanisms remain unclear." (PMID 28882992, 2017).
Pancytopenia (1 paper, 2012). An abnormal reduction in numbers of all blood cell types (red blood cells, white blood cells, and platelets). "Furthermore, mice with AML induced by co-expression of BCR/ABL and the Nup98/HoxA9 fusion protein showed a loss of osteolineage cells in the marrow, which may have contributed to the underlying pancytopenia." (PMID 22952867, 2012).
pemphigus (1 paper, 2024). Pemphigus is a group of rare autoimmune diseases that cause blistering of the skin and mucous membranes (mouth, nose, throat, eyes, and genitals).This conditioncan occur at any age, but often strikes people in middle or older age. "The data from the SCID xenograft mice and BCR sequencing together indicate that lesional Dsg-specific B cells might circulate among lymph nodes, peripheral blood and pemphigus lesions." (PMID 39654895, 2024).
pericarditis (1 paper, 2024). An inflammatory process affecting the pericardium. "Age-stratified analysis showed significant signals in the younger patients group for endocardial disorders with ponatinib (BCR-ABL) and pericarditis with brigatinib (ALK), with no reports in the older patients group." (PMID 39687301, 2024).
pleomorphic xanthoastrocytoma (1 paper, 2026). A WHO grade ll astrocytic tumor with a relatively favorable prognosis. "In the same study, a case of PA bore a fusion of breakpoint cluster region (BCR) and NTRK2 genes (BCR-NTRK2), while a patient with pleomorphic xanthoastrocytoma (PXA) harbored the tropomyosin 3 (TPM3)-NTRK1 fusion." (PMID 41514664, 2026).
polycythemia (1 paper, 2006). Abnormally high mass or concentration of red blood cells in the blood, either due to an increase in erythropoiesis or a decrease in plasma volume. "In complementary studies where diseased mice were treated with dasatinib, a potent inhibitor of both ABL and Src kinases, there was minimal response of polycythemia and reticulocytosis to a regimen that is very effective for treatment of mice inoculated with BCR-ABL-expressing cells." (PMID 17183644, 2006).
primary immunodeficiency (1 paper, 2023). "The findings showed that high expression of LINC02577 inhibited signaling by the B cell receptor BCR, t-helper pathway and primary immunodeficiency." (PMID 37173624, 2023).
prostate adenocarcinoma (1 paper, 2022). "Moreover, for three of these proteins, NPM1NPM1, VCAN, and UQCRH, we were able to validate their relative increase in BCR+ compared to BCR- using prostate adenocarcinoma mRNA data in TCGA." (PMID 35954429, 2022).
renal tumors (1 paper, 2025). "BCR mutations are infrequent in solid tumors; however, its alterations have been linked to certain renal tumors, particularly MC-LMP." (PMID 40860802, 2025).
respiratory failure (1 paper, 2025). The significant impairment of gas exchange within the lungs resulting in hypoxia, hypercarbia, or both, to the extent that organ tissue perfusion is severely compromised. "In terms of complications, respiratory failure, AKI, and DM changed significantly with increasing BCR (all P values <0.05)." (PMID 40110543, 2025).
retinoblastoma (1 paper, 2025). A malignant tumor that originates in the nuclear layer of the retina. "KEGG analysis revealed five pathways positively associated with DBF4B expression: retinoblastoma gene cancer, resolution of sister chromatid, CD22-mediated BCR regulation, kinesins, and the role of phospholipids in phagocytosis." (PMID 40535802, 2025).
rheumatic diseases (1 paper, 2022). "Incorporation of TCR and BCR repertoire data into scRNAseq thus offers an exciting new lens for analyzing and understanding the pathogenesis of rheumatic diseases, and may shed light on the true behavior of autoreactive clones in rheumatic diseases." (PMID 35251048, 2022).
Richter syndrome (1 paper, 2017). Transformation of chronic lymphocytic leukemia into aggressive non-Hodgkin's lymphoma, usually diffuse large B-cell lymphoma (immunoblastic or centroblastic variant). "In the absence of NFAT2, BCR stimulation leads to enhanced phosphotyrosine induction and calcium flux culminating in the activation of AKT and ERK and subsequent cell proliferation which can be observed in patients with aggressive forms of CLL or Richter’s syndrome." (PMID 28970470, 2017).
sarcoidosis (1 paper, 2024). Sarcoidosis is a multisystemic disorder of unknown cause characterized by the formation of immune granulomas in involved organs. "Flow cytometry analysis revealed that the frequency of blood NK cells appeared to be increased in several uveitis subtypes (Serpiginous, Definite Sarcoidosis and Birdshot), but this increase was most significant for BCR-UV (Birdshot, P < 0.0001)." (PMID 39085199, 2024).
sarcopenia (1 paper, 2022). Progressive decline in muscle mass due to aging which results in decreased functional capacity of muscles. "It should be noted that the underlying mechanisms of how sarcopenia and a low BCR can contribute to hypoactive delirium were beyond the scope of this study." (PMID 36078999, 2022).
seminoma (1 paper, 2020). A radiosensitive malignant germ cell tumor found in the testis (especially undescended), and extragonadal sites (anterior mediastinum and pineal gland). "For example, a frameshift mutation in BCR, present in both TC1 and TC4 models, has previously been observed in a non-seminoma TC patient tumour (cBioportal)." (PMID 33144587, 2020).
Stroke (1 paper, 2025). Sudden impairment of blood flow to a part of the brain due to occlusion or rupture of an artery to the brain. "A prospective cohort study of over 50,000 participants, with an average follow-up of 7.9 years, found that elevated BCR levels were linked to a higher stroke risk." (PMID 40110543, 2025). "Moreover, the potential of the BCR as a prognostic marker for stroke is underlined by a large sample study showing a significant 19% increase in stroke risk in participants in the lowest quintile compared with those in the third quintile of the BCR." (PMID 40110543, 2025).
Tinnitus (1 paper, 2020). Tinnitus is an auditory perception that can be described as the experience of sound, in the ear or in the head, in the absence of external acoustic stimulation. "The results could support the suggestion that the BCR gene is implicated in the process of making tinnitus distress severe." (PMID 32747715, 2020). "Although the STAI-state score was identified as cofounder between THI score and SNP rs131702 of the BCR gene, it could mean that the patients with SNP rs131702 of BCR gene have potential to suffer from more severe tinnitus." (PMID 32747715, 2020).
tuberculosis (1 paper, 2020). A chronic, recurrent infection caused by the bacterium Mycobacterium tuberculosis. "The widely available GeneXpert (Cepheid) machines in Sub-Saharan Africa for tuberculosis testing, can now be adapted for BCR-ABL fusion gene diagnostics." (PMID 32374771, 2020).
tumor (270 papers, 2004 to 2026). "Some failures occur because of tumor-derived mutations in the BCR-ABL target, which has spurred the development of second-generation TKIs." (PMID 38646295, 2024). "Tumor resistance is the leading cause of treatment failure, most commonly through point mutations in the BCR-ABL kinase domain, with T315I being the most well-studied and frequent mutation." (PMID 38646295, 2024). "Under the assumption that acquisition of a potential oncogenic subclonal mutation occurs alongside BCR diversification, BCRs can serve as markers in the study of clonal evolution in FL tumours." (PMID 39501370, 2024). "Over-activation of the JAK signaling pathway and dysregulation in the BCR or TCR signaling pathways are closely associated with tumor growth." (PMID 37189408, 2023). "A clear trend towards faster tumor cell engraftment and proliferation was obvious in BCR::ABL1-mutated samples (four out of five), as well as T-ALLs." (PMID 35011712, 2022). "CD79B mutations were shown to cause chronic activation of BCR signaling and constitutive NF-κB activation, further promoting tumor cell growth within the immunosuppressive TME." (PMID 34745101, 2021). "Kaplan–Meier analysis confirmed that PTENLOW and CXCR1/2HIGH tumours were associated with a significantly reduced time to BCR (P < 0.001; HR 2.65) and importantly with the development of metastasis (P = 0.002; HR 3.51) after RT treatment." (PMID 32743555, 2020). "Aberrant PI3K/AKT pathway activation via activating PI3K mutations, amplification of genes encoding HER2, EGFR and AKT, BCR-ABL translocation or PTEN loss leads to decreased autophagy in many tumor cells largely through mTOR activation." (PMID 31438969, 2019). "When the respective phosphorylation sites were mutated in SOCS-1 or SOCS-3, BCR-ABL induced tumor formation was completely blocked in nude mice due to “activation” of SOCS-1 or SOCS-3." (PMID 28753604, 2017). "Cytotoxicity against a tumor cell line endogenously expressing the p210 (BCR-ABL) b3a2 variant fusion region was also demonstrated." (PMID 23241263, 2012). "It correlates secondly with the angiogenesis process, linking the BCR/ABL fusion protein to VEGF (vascular endo-thelial growth factor) gene expression which is a hallmark of tumor aggressiveness." (PMID 16674810, 2006). "In addition, we observed strong positive associations between CAF and TGF-beta response, and between B_Non-regulatory state and BCR diversity, these two signatures have been respectively linked to a suppressive immune response and a robust anti-tumor response." (PMID 38082384, 2023). "Finally, we found IC50 of the anti-tumor compounds was usually lower in the low-risk group, such as Bosutinib, a dual kinase inhibitor of both the BCR-ABL and Src tyrosine kinases." (PMID 35754840, 2022). "This comparison is possible because we corrected the tumor burden value observed in the RNA method by the disease level of each patient at that time multiplying the variant allele frequency of the mutation by the BCR::ABL1/ABL1 ratio." (PMID 35906470, 2022). "FL tumor-associated macrophages have been shown to play a key role in the growth of FL B cells through the transpresentation of IL-15 and the triggering of BCR-dependent signaling involving DC-SIGN-expressing macrophages and oligomannose residues introduced in FL BCR." (PMID 34956214, 2021). "In order to elucidate whether Aid is indeed functional prior to pre-BCR expression, we developed an Aid-deficient mouse model with a tumor prone Rag1-/- background (p19Arf-/-Rag1-/-Aid-/- ARA)." (PMID 29100269, 2017). "To assess whether the observed BCR dynamics upon tumor transplantation are also associated with clonal evolution of somatic mutations, we performed WES of serially transplanted tumors R62, Q76, Q67, and Q82 and compared mutation profiles with matched original primary tumors." (PMID 30262843, 2019).